SRI (sorcin)
Diseases named in the same sentence as SRI in open-access papers (continued):
Sharing a sentence is not in itself a finding about the gene and the disease.
pancreatic cancer (2 papers, 2024). "Within the scope of eight genes associated with pancreatic cancer, we detected two variants, namely rs6465133 (SRI) (p = 0.001) and rs61759623 (KRAS) (p = 0.005), which exhibit the potential to differentiate between PCAND and T2DM." (PMID 39526476, 2024). "In addition, in biopsies obtained from 88 PDAC patients, we detected elevated expression of sorcin in pancreatic cancer tissues, especially in PCAND." (PMID 39516378, 2024). "Researchers investigated the connection between pancreatic cancer and newly developed diabetes, pinpointing the SRI gene and its protein, sorcin, as crucial elements." (PMID 39516378, 2024). "To investigate how sorcin upregulation may lead to islet dysfunction in PCAND, we utilized in vitro cell cultures to mimic the interactions between pancreatic cancer and islet tissue." (PMID 39516378, 2024). "However, the expression levels of sorcin were similar in tumor samples of different TNM stages in our cohort, probably because the TNM stage is a macroscopic and anatomy-dependent system that may not reflect the cancerous behavior of pancreatic cancer." (PMID 39516378, 2024).
Parkinson disease (2 papers, 2020 to 2021). A progressive degenerative disorder of the central nervous system characterized by loss of dopamine producing neurons in the substantia nigra and the presence of Lewy bodies in the substantia nigra and locus coeruleus. "Few studies have identified the connection of sorcin to several proteins involved in Parkinson’s Disease and other Lewy body diseases, such as α-synuclein and synplilin-1, using phage display and gene co-expression analysis." (PMID 34205207, 2021).
acute myeloid leukemia (1 paper, 2021). Acute myeloid leukemia (AML) is a group of neoplasms arising from precursor cells committed to the myeloid cell-line differentiation. "The SRI overexpression was reported to be closely related to the poor clinical outcomes and the complete remission rate in acute myeloid leukemia." (PMID 34869449, 2021).
astrocytic tumor (1 paper, 2022). A glial tumor of the brain or spinal cord showing astrocytic differentiation. "EGFR is the most frequently amplified oncogene in astrocytic tumors; expression of genes SRI, NPTX2, MEST, RARRES2, and SEPTIN7 in association with GBM is reported in this study." (PMID 35327982, 2022).
astrocytoma (1 paper, 2010). "Sorcin mRNA and protein levels have been reported in astrocytoma and are positively correlated with the malignancy of the tumor." (PMID 20181261, 2010).
cardiomyopathy (1 paper, 2014). A disease of the heart muscle or myocardium proper. "Overexpression of Sorcin leads to dysregulation of Ca2+ signaling and deterioration of cardiac function under conditions of cardiomyopathy, whereas the siRNA-mediated knockout of Sorcin leads to the recovery of cardiac contractility in cardiac-specific Dicer knockout mice." (PMID 25216032, 2014).
diabetes (1 paper, 2020). "We think that studies on the recently obtained sorcin−/− knock out mouse will give important information on the roles of sorcin not only in cancer and in MDR, but also in brain and muscle development, in lipid metabolism, in diabetes, and in neurodegenerative diseases." (PMID 32268494, 2020).
diabetic cardiomyopathy (1 paper, 2020). Diabetic cardiomyopathy is a disorder of the heart muscle in people with diabetes. "Sorcin overexpression enhances cardiac contractility and reverses contractile anomalies of diabetic cardiomyopathy, while sorcin KO mice exhibit arrhythmias and sudden death under acute or chronic stress, due to disturbances of Ca2+ fluxes." (PMID 32268494, 2020).
fatty liver disease (1 paper, 2021). A reversible condition wherein large vacuoles of triglyceride fat accumulate in liver cells via the process of steatosis. "As our focus was to understand the importance of sorcin in regulating high carbohydrate diet–induced ChREBP-driven hepatic steatosis, it seemed imperative to understand the mechanism behind sorcin downregulation." (PMID 33930463, 2021). "Based on these findings, we propose that the NF-κB p65–Sorcin–ChREBP cytosolic complex to be a potential site for pharmacological interventions as an effective therapy for reducing high carbohydrate diet–induced fatty liver disease." (PMID 33930463, 2021).
heart failure (1 paper, 2024). Inability of the heart to pump blood at an adequate rate to meet tissue metabolic requirements. "Sorcin has a critical role in maintaining Ca2+ homeostasis, especially during the adrenergic response of the heart: in a sorcin knockout (KO) mouse model, sorcin deficiency can lead to ventricular arrhythmias and heart failure." (PMID 39199583, 2024).
Hepatitis (1 paper, 2017). Inflammation of the liver. "To investigate the role of sorcin in inflammatory response and the underlying molecular mechanisms, we generated mice deficient of sorcin (sorcin−/−) and induced hepatitis in sorcin−/− mice with ConA." (PMID 28706517, 2017). "Here, we show that mice deficient of sorcin (sorcin−/−) display enhanced ConA-induced hepatitis." (PMID 28706517, 2017). "Sorcin−/− mice developed severe hepatitis post injection with ConA, which was characterized by widespread lesions, inflammatory infiltrates, and hepatocyte death." (PMID 28706517, 2017). "Our data from the present study show that sorcin−/− mice has enhanced inflammatory response to ConA-induced hepatitis and cytokine expressions, providing direct evidence to show that sorcin plays an important role as a negative regulator in immune response." (PMID 28706517, 2017). "Sorcin+/+ and sorcin−/− mice were injected intravenously with ConA, and hepatitis in mice was measured by anatomical and histological examinations of the liver and blood transaminase assays." (PMID 28706517, 2017). "In contrast, sorcin+/+ displayed mitigated hepatitis with the same treatment." (PMID 28706517, 2017). "In summary, our data show that sorcin−/− animals display enhanced ConA-induced hepatitis and express more cytokines (IL-2, IL-4, IL-17, and IFN-γ) than the wild-type controls, indicating that sorcin acts as a negative regulator in immune response in vivo." (PMID 28706517, 2017).
myelogenous leukemia (1 paper, 2015). "Among these proteins, enolase, aldolase, HSP70 and sorcin were up-regulated in doxorubicin-resistant myelogenous leukemia cell line, whereas HSP27 was down-regulated." (PMID 25628518, 2015). "In our present study, several calcium-binding proteins were identified in doxorubicin-resistant myelogenous leukemia cells, such as sorcin, protein S100-A4, annexin A4, calreticulin, etc., indicating that metal ions such as calcium might play a pivotal role in the development of chemoresistance." (PMID 25628518, 2015).
non-small cell lung adenocarcinoma (1 paper, 2025). Type of epithelial lung cancer arising from glandular origin. "Our previous work demonstrated that Sorcin regulates EGFR signaling in non-small cell lung adenocarcinoma, promoting cellular invasion and migration." (PMID 41148307, 2025).
prostate carcinoma (1 paper, 2025). A carcinoma that arises from epithelial cells of the prostate gland. "This study aims to compare the histopathology results of serum sorcin level and tissue sorcin immunohistochemical expression in PCa patients who underwent radical prostatectomy (RP), with the goal of elucidating the correlation between sorcin and prostate cancer." (PMID 40611756, 2025). "It was hypothesized that sorcin might be overexpressed in prostate cancer patients." (PMID 40611756, 2025).
schizophrenia (1 paper, 2016). A major psychotic disorder characterized by abnormalities in the perception or expression of reality. "A study of the protein changes in ACC in schizophrenia, MDD and bipolar disorder found that cytoskeletal and mitochondrial proteins are the most prominently altered in all of these disorders, but only 2 identified proteins (SRI, ALDOC) were found with changed levels in both schizophrenia and MDD." (PMID 26909022, 2016).
thymoma (1 paper, 2024). A neoplasm arising from the epithelial cells of the thymus. "It was discovered that A2M, C3, LGALS3BP, PMFBP1, and SRI were remarkably upregulated in individuals with thymoma (P < 0.05)." (PMID 39434140, 2024).
virus infection (1 paper, 2017). "In our previous study, our data show that FMDV VP1 suppresses type I interferon expression via interaction with sorcin that negatively regulates cell response to virus infection." (PMID 28706517, 2017).
cancer (28 papers, 2009 to 2025). A tumor composed of atypical neoplastic, often pleomorphic cells that invade other tissues. "SRI, which was the only gene up-regulated at the mRNA and protein level in all three PR PDAC models alongside ABCB1, encodes the calcium-binding protein Sorcin that is associated with cancer progression and can activate expression of ABCB1." (PMID 38163893, 2024). "It appears that dysregulated Sorcin expression is closely linked to the occurrence, invasion, metastasis, and progression of cancer in numerous human tumors." (PMID 37833249, 2023). "Indeed, the overexpression of Sorcin has been associated with several cancer cell types, especially in those resistant to chemotherapeutic treatments." (PMID 37442828, 2023). "Sorcin, a penta-EF hand calcium-binding protein, is implicated in multidrug resistance (MDR) in various cancers and has roles in neurodegenerative diseases." (PMID 41133884, 2025). "Sorcin (soluble resistance related calcium binding protein) is one of the signaling molecule that has recently received more attention in cancer research as it has been found to induce multidrug resistance (MDR) in cancers." (PMID 40611756, 2025). "The serum level of sorcin, which has been shown to be overexpressed in many cancer types, was found to be higher in PCa patients compared to the healthy male population." (PMID 40611756, 2025). "Sorcin and EGFR expression levels are significantly correlated and linked to decreased overall survival in cancer patients." (PMID 39199583, 2024). "Soluble resistance-related calcium-binding protein (sorcin, SRI) is a 22-kDa, soluble, small, penta EF family (PEF) of calcium (Ca2+)-binding protein which has an association with cancer development." (PMID 39000312, 2024). "A recent study investigated the expression of sorcin in normal tissues vs. cancer tissues using multiple databases, i.e., Genotype-Tissue Expression (GTEX), The Cancer Genome Atlas (TCGA), and Oncomine." (PMID 39199583, 2024). "Since Sorcin is overexpressed in different types of tumors and is involved in the calcium-linked regulation of pathways triggered by EGFR, we investigated the role of Sorcin in EGF-dependent invasion of cancer cells." (PMID 37442828, 2023). "For example, overexpression and amplification of the calcium-binding protein Sorcin has been described for different cancer entities, including lung cancer." (PMID 38016997, 2023). "Sorcin and EGFR showed association with survival in the majority of the considered cancer types even when evaluated individually." (PMID 37442828, 2023). "This analysis evidenced that high levels of expression of both Sorcin and EGFR, considered as a signature, is associated with reduced overall survival in various cancer types, compared to low expression." (PMID 37442828, 2023). "Sorcin and EGFR expression are significantly correlated and associated with reduced overall survival in cancer patients." (PMID 37442828, 2023). "This includes functionally relevant proteins associated with LN metastasis in cancer such as KRT7, KRT19, SRI, NPM1, Annexin A2 (ANXA2), Annexin A5 (ANXA5)." (PMID 37142981, 2023). "Sorcin is a 22 kDa soluble resistance related calcium-dependent protein reported to be involved in multidrug resistance in cancer." (PMID 37142981, 2023). "Sorcin (SRI) is a soluble resistance-related calcium-binding protein, which is overexpressed in many malignant tumors." (PMID 35799174, 2022). "To uncover the role of SRI in pan-cancer, we systematically integrated multiple databases from bioinformatics point of view." (PMID 34869449, 2021). "The overexpression of sorcin contributed to resistance to many chemotherapy agents, and sorcin knockdown has been found to reverse the multidrug resistance in certain types of cancer." (PMID 34869449, 2021). "The SRI gene was altered in 168 patients with cancer which accounted for only 1.5% across 10,953 samples." (PMID 34869449, 2021).
cancer (continued). "In particular, sorcin and DBF4 overexpression are drivers of MDR in several types of cancers; the development of inhibitors of sorcin expression and of CDC7-DBF4 activity as potential anti-tumor candidates was recently accomplished." (PMID 32268494, 2020). "Sorcin is expressed at high levels in many cancers, from many different tissues, usually with MD-resistant phenotype dependent on ABCB1 expression." (PMID 32268494, 2020). "Here, we used immunohistochemistry to confirm that the expression of sorcin in cancer tissues is higher than that in the adjacent normal tissues." (PMID 29262638, 2017). "Sorcin (Sri) is highly expressed in the heart and in the brain, and overexpressed in many cancer cells in general and in AML." (PMID 27250028, 2016). "Sorcin is an essential penta-EF hand calcium binding protein, able to confer the multi-drug resistance phenotype to drug-sensitive cancer cells and to reduce Endoplasmic Reticulum stress and cell death." (PMID 26577048, 2015). "Sorcin participates in the modulation of calcium homeostasis and in calcium-dependent cell signalling in normal and cancer cells." (PMID 26577048, 2015). "Sorcin appears to be located at many important crossroads of human cells, and to have an important role on the onset of cancer, cardiac diseases and neurodegenerative diseases." (PMID 25197934, 2014). "Sorcin, a protein overexpressed in many multi-drug resistant cancers, dynamically localizes to distinct subcellular sites in 3T3-L1 fibroblasts during cell-cycle progression." (PMID 24427308, 2014). "Sorcin overexpression results in increased resistance to many important anti-cancer drugs, and sorcin silencing is able to revert drug resistance." (PMID 25197934, 2014). "Sorcin is highly expressed in the heart and in the brain, and is overexpressed in many cancer cells, being co-amplified with other proteins involved in the resistance to chemotherapy in cancer cells, as the ABC transporters ABCB4 and ABCB1." (PMID 25197934, 2014). "Sorcin gene is located in chromosome 7, in the same amplicon of other genes involved in the resistance to chemotherapeutic agents in cancer cells (multi-drug resistance, MDR), as the ABC transporters ABCB4 and ABCB1 (Mdr1, or P-glycoprotein 1)." (PMID 25197934, 2014). "Although the levels of expression of sorcin is much lower than that of calmodulin, sorcin is differentially expressed in cancers and other pathological conditions and is able to interact with a series of crucial targets and to regulate them." (PMID 25197934, 2014). "Sorcin, a signaling molecule, has recently emerged as a significant focus within cancer research." (PMID 40611756, 2025). "Overexpression of sorcin in the advanced prognosis of cancer may be a marker of poor prognosis in PCa." (PMID 40611756, 2025). "Furthermore, sorcin overexpression via gene transfection enhances drug resistance to various chemotherapeutic drugs across numerous cancer lines." (PMID 39199583, 2024). "Sorcin overexpression seems to contribute to cancer cell survival by means of different features." (PMID 39199583, 2024). "Based on the significant fold change in LN positive GBC in mass spectrometric data and literature survey for their functional relevance and association with LN metastasis in cancer, we selected four proteins namely KRT7, KRT19, SRI and NPM1 for verification using Western blot analysis." (PMID 37142981, 2023). "Sorcin, a small penta-EF hand calcium sensor, exhibits mitosis specific changes in cellular localisation and is over-expressed in multiple human cancers." (PMID 35784871, 2022). "Furthermore, SRI was overexpressed, while intracellular calcium concentration was decreased, in chemoresistant cancer cells." (PMID 35799174, 2022). "Sorcin is highly expressed in the heart and in the brain, and overexpressed in many cancer cells." (PMID 25197934, 2014).